UCHL5 (ubiquitin C-terminal hydrolase L5)
Diseases named in the same sentence as UCHL5 in open-access papers (continued):
Sharing a sentence is not in itself a finding about the gene and the disease.
liver cancer (5 papers, 2017 to 2024). An epithelial or non-epithelial malignant neoplasm that arises from the liver. "It was found that UCHL5 facilitated filopodia formation in liver cancer cells by regulating FSCN1, which was associated with FASN." (PMID 39075049, 2024). "Prognostically, it was found that high UCHL5 mRNA level was associated with a poor prognosis in liver cancer patients." (PMID 39075049, 2024). "And the mRNA levels of ADRM1 and UCHL5 presented a direct correlation in normal and liver cancer specimens, as well as ADRM1 and FASN." (PMID 39075049, 2024). "Molecularly, the Co-IP assays showed that endogenous UCHL5 interacted with FASN in liver cancer cells." (PMID 39075049, 2024). "Previously, we reported UCHL5 as a positive regulator of Wnt signaling pathway in Xenopus embryos and HepG2 liver cancer cell." (PMID 35256667, 2022). "It was found that the mRNA of UCHL5 was high expressed in liver cancer." (PMID 39075049, 2024). "Furthermore, we collected clinical samples to determine the protein level of UCHL5 and found that the protein of UCHL5 was higher in liver cancer tissues than normal liver tissues." (PMID 39075049, 2024). "To explore whether UCHL5 acts as an upstream deubiquitinating enzyme for FASN in human liver cancer cells, we first analyzed the roles of UCHL5 in the regulation of FASN protein level in HepG2 and Huh7 cells." (PMID 39075049, 2024). "Functionally, we determined whether UCHL5 could regulate filopodia formation in liver cancer cells." (PMID 39075049, 2024). "And the mRNA levels of UCHL5 and FASN presented a direct correlation in normal and liver cancer specimens." (PMID 39075049, 2024). "Correspondingly, the protein levels of UCHL5 and FASN also presented a direct correlation in normal and liver cancer specimens." (PMID 39075049, 2024). "To investigate the clinical significance of UCHL5 and FASN, we first detected the mRNA level of UCHL5 in liver cancer via database." (PMID 39075049, 2024). "Since UCHL5 exerts its role as a deubiquitinating enzyme through recruitment and activation by ADRM1 (adhesion regulating molecule 1), also known as Rpn13, we further explored the regulation and mechanism of action of ADRM1 on FASN in liver cancer." (PMID 39075049, 2024). "In this study, we determined that ADRM1-activated UCHL5 was upregulated in liver cancer and stabilized FASN through deubiquitinating it, thereby promoting the expression of FSCN1 and filopodia formation in human liver cancer cells, as well as cell movement." (PMID 39075049, 2024).
bladder cancer (4 papers, 2022 to 2024). "UCHL5 is overexpressed in patients with bladder cancer patients, and high expression is associated with poor prognosis and tumor progression." (PMID 37497216, 2023). "According to these results, we conclude that UCHL5 is significantly linked to the onset and spread of bladder cancer." (PMID 36428630, 2022). "In conclusion, we found that UCHL5 is overexpressed in bladder cancer patients, and that high UCHL5 expression is associated with aggressive tumor characteristics and a poor prognosis." (PMID 36428630, 2022). "Our findings indicate that UCHL5 is a valuable diagnostic marker and potential therapeutic target for bladder cancer." (PMID 36428630, 2022). "Thus, we also wanted to know whether the UCHL5 was associated with some immune cell types in bladder cancer." (PMID 36428630, 2022). "Meanwhile, it has been reported that the UCHL5 inhibitor b-AP15 suppresses bladder cancer stemness by inhibiting the β-catenin and c-Myc signaling pathways and overcomes cisplatin resistance." (PMID 37497216, 2023). "UCHL5 is abnormally upregulated in human cancer tissues and cell lines, such as pancreatic adenocarcinoma, gastric cancer, endometrial cancer, and bladder cancer." (PMID 37497216, 2023). "Using shRNA-mediated knockdown and overexpression of UCHL5, we confirm that UCHL5 regulates c-Myc expression in bladder cancer cells." (PMID 36428630, 2022). "In this study, we demonstrate that ubiquitin C-terminal hydrolase-L5 (UCHL5), a member of the DUBs family, promotes the growth and migration of bladder cancer cells and facilitates tumor growth in vitro." (PMID 36428630, 2022). "By contrast, overexpression of UCHL5 in bladder cancer cell lines aggravated its proliferation and migration." (PMID 36428630, 2022). "In this study, we showed that the deubiquitinating enzyme UCHL5 is abnormally elevated in bladder cancer." (PMID 36428630, 2022). "In contrast to adjacent tissue samples, we discovered that UCHL5 was substantially expressed in bladder cancer samples." (PMID 36428630, 2022). "In the following experiment, we upregulated the UCHL5 expression in bladder cancer cells through lentivirus infection." (PMID 36428630, 2022). "From these results, we infer that UCHL5 regulates the proliferation and migration of bladder cancer cells through the AKT/mTOR signaling pathway." (PMID 36428630, 2022). "This newly defined UCHL5-AKT/mTOR-c-Myc axis represents a new therapeutic target for the treatment of bladder cancer." (PMID 36428630, 2022). "Then, we utilized tissue microarrays, including 63 bladder cancer tissue samples and 16 adjacent bladder tissue samples, using IHC analysis of UCHL5 to verify the earlier findings." (PMID 36428630, 2022). "Several procedures were performed to assess the effect of UCHL5 overexpression or knockdown on bladder cancer, such as cell proliferation, colony formation, wound-healing, and Transwell assays." (PMID 36428630, 2022). "According to RNA-Seq analyses and Western blotting experiments, the expression of c-Myc, SLC25A19, and ICAM5 was modified as a result of UCHL5 activating AKT/mTOR signaling in bladder cancer cells." (PMID 36428630, 2022). "In this study, we found that UCHL5 is substantially expressed in bladder cancer tissues and cells." (PMID 36428630, 2022). "We infer from these findings that UCHL5 is an essential determinant of bladder cancer progression." (PMID 36428630, 2022). "This study investigates the expression and function of UCHL5 in bladder cancer." (PMID 36428630, 2022). "Associations between UCHL5 and cancer have been reported in various tissues, but the effect of UCHL5 on bladder cancer has not been thoroughly investigated." (PMID 36428630, 2022). "Although UCHL5 is shown to be an oncogene in many malignancies, its function in bladder cancer remains unknown." (PMID 36428630, 2022).
bladder cancer (continued). "Finally, bladder cancers with knockdown or overexpression of UCHL5 were treated with either SC79 or LY294002 to examine the participation of the AKT/mTOR signaling pathway and the expression of downstream targets c-Myc, SLC25A19, and ICAM5." (PMID 36428630, 2022). "UCHL5 is therefore a potential target for therapy in bladder cancer patients." (PMID 36428630, 2022). "Although many malignancies have revealed UCHL5 to be an oncogene, its function in bladder cancer is yet unknown." (PMID 36428630, 2022). "Therefore, UCHL5 is a potential target for therapy in bladder cancer." (PMID 36428630, 2022). "Nevertheless, the exact roles of UCHL5 in bladder cancer cells remain unclear." (PMID 36428630, 2022). "Then, SC79 (activator of AKT) was used to treat bladder cancer cells transfected with UCHL5 shRNA, and Western blotting analysis showed rescue of p-AKT/p-mTOR protein expression affected by UCHL5 knockdown." (PMID 36428630, 2022). "Ubiquitin C-terminal hydrolase-L5 (UCHL5), a member of the DUBs family of proteins that is overexpressed in bladder cancer, has been indicated to promote the growth and migration of bladder cancer cells by increasing MYC expression through the AKT/mTOR signaling pathway." (PMID 39031286, 2024). "In addition to discovering that the AKT/mTOR pathway is involved in regulating the progression of bladder cancer, we also identified downstream target proteins (c-Myc, SLC25A19, and ICAM5) of UCHL5 by RNA-Seq." (PMID 36428630, 2022). "All things considered, our findings show that increased UCHL5 expression stimulates AKT/mTOR signaling, subsequently triggering the expression of c-Myc, SLC25A19, and ICAM5, which in turn promotes carcinogenesis in bladder cancer." (PMID 36428630, 2022).
colorectal cancer (4 papers, 2017 to 2025). A primary or metastatic malignant neoplasm that affects the colon or rectum. "The roles of USP14 and UCHL5 in cancer have indeed been examined in various contexts, including colorectal cancer and chronic myeloid leukemia." (PMID 40804247, 2025). "We have recently demonstrated that patients with high tumor immunoexpression of the deubiquitinating enzyme UCHL5/Uch37 had better prognosis in colorectal cancer (CRC) and pancreatic ductal adenocarcinoma (PDAC)." (PMID 29474458, 2018).
glioma (4 papers, 2017 to 2023). A benign or malignant brain and spinal cord tumor that arises from glial cells (astrocytes, oligodendrocytes, ependymal cells). "Among the selected DUBs significantly linked to the DNA damage repair pathway, the glioma and MB datasets shared several DUBs, including USP1, USP47, UCHL5, and OTUD1, which cover five major DNA damage repair pathways (BER, NER, FA, TLS, DSB)." (PMID 37892185, 2023).
lymph node metastasis (3 papers, 2019 to 2020). "A high expression level of UCHL5 was closely associated with a larger tumor size, early lymph node metastasis and advanced TNM, which predicted poor OS and DFS of patients with LUAD." (PMID 33046988, 2020). "The results showed that the UCHL5 expression level was associated with tumor size, lymph node metastasis, TNM stage and malignant tumor history in patients with LUAD." (PMID 33046988, 2020).
acute myeloid leukemia (2 papers, 2015 to 2020). Acute myeloid leukemia (AML) is a group of neoplasms arising from precursor cells committed to the myeloid cell-line differentiation. "We have demonstrated that CuPT and auranofin are the novel metal inhibitors of UCHL5 and USP14 of the 19S proteasome by using several tumor models, including hematological malignancies, several solid tumor models and primary cells of the acute myeloid leukemia patients." (PMID 26097878, 2015).
colon cancer (2 papers, 2014 to 2022). "Only HSP90AB1, RIPK2, DDX21, UCHL5, GTPBP4, and PCID2 were significantly different in UC and COAD tissues, and they all showed overexpression in colon cancer tissues compared to UC tissues." (PMID 35372018, 2022). "In order to gain insight into the mechanisms through which the USP14/UCHL5 inhibitor b-AP15 kills cells, we compared the effect of this compound on HCT116 colon cancer cells and non-malignant hTERT-RPE1 cells." (PMID 25286379, 2014).
idiopathic pulmonary fibrosis (2 papers, 2016 to 2019). Idiopathic pulmonary fibrosis (IPF) is a nonneoplastic pulmonary disease that is characterized by the formation of scar tissue within the lungs in the absence of any known cause. "But the role of UCHL5 in regulation of Smad2/Smad3 and pathogenesis of pulmonary fibrosis is still unclear." (PMID 27604640, 2016). "This study, at least, provides evidence that inhibition of UCHL5 lessens severity of pulmonary fibrosis in a pre-clinical animal model." (PMID 27604640, 2016). "b-AP15, an inhibitor of UCHL5, attenuates TGFβ-1 signaling and diminishes pulmonary fibrosis in a bleomycin-induced pulmonary fibrosis model." (PMID 27604640, 2016). "Next, we examined levels of UCHL5, Smad2 and Smad3 in murine lungs from a bleomycin-induced pulmonary fibrosis model." (PMID 27604640, 2016). "To further investigate the role of UCHL5 in TGFβ-1 signaling and pulmonary fibrosis, first, we examined the UCHL5 expression in lungs from IPF patients." (PMID 27604640, 2016). "Here, we demonstrate that UCHL5 de-ubiquitinates and stabilizes Smad2 and Smad3, thereby promoting TGFβ-1 signaling and contributes to the pathogenesis of pulmonary fibrosis." (PMID 27604640, 2016). "This study reveals that inhibition of UCHL5 is a potential therapeutic strategy for pulmonary fibrosis treatment." (PMID 27604640, 2016). "In conclusion, we demonstrate that UCHL5 de-ubiquitinates and stabilizes Smad2 and Smad3, promotes TGFβ signaling, and contributes to the pathogenesis of pulmonary fibrosis." (PMID 27604640, 2016). "Targeting UCHL5 has the potential for pulmonary fibrosis treatment." (PMID 27604640, 2016). "Future study will focus on the molecular regulation of UCHL5 expression in lung fibrosis." (PMID 27604640, 2016). "This is the first study to identify that UCHL5 plays a pro-fibrotic role in the pathogenesis of pulmonary fibrosis through stabilization of Smad2/Smad3 and enhance in TGFβ-1 signaling in HLF and a murine model of pulmonary fibrosis." (PMID 27604640, 2016). "Administration of UCHL5 inhibitor, b-AP15, reduced the expression of FN, type I collagen, Smad2/Smad3, and the deposition of collagen in lung tissues in a bleomycin-induced model of pulmonary fibrosis." (PMID 27604640, 2016).
leukemia (2 papers, 2022 to 2024). A malignant (clonal) hematologic disorder, involving hematopoietic stem cells and characterized by the presence of primitive or atypical myeloid or lymphoid cells in the bone marrow and the blood. "This study demonstrated that the USP14/UCHL5 inhibitors b-AP15 and AUR effectively inhibited the K48-mediated deubiquitination of ubiquitin bound to FLT3 in leukemia cells with FLT3-ITD mutations." (PMID 39408703, 2024). "First, we investigated the effects of b-AP15, a specific inhibitor of USP14/UCHL5, and AUR, a gold compound with similar inhibitory activity, on the cell cycle of leukemia cell lines." (PMID 39408703, 2024). "Apoptosis induction in leukemia cells through USP14 inhibition has been previously documented; however, this is the first study to identify a specific mechanism by which USP14/UCHL5 inhibition induces apoptosis in FLT3-ITD-positive AML cells or in primary FLT3-ITD-positive AML cultures." (PMID 39408703, 2024).
lung adenocarcinoma (2 papers, 2020 to 2024). A carcinoma that arises from the lung and is characterized by the presence of malignant glandular epithelial cells. "The level of UCHL5 was associated with tumor size, lymph node invasion, TNM stage and malignant tumor history in patients with lung adenocarcinoma (LUAD)." (PMID 33046988, 2020).
lung carcinoma (2 papers, 2020 to 2025). "Although previous studies have shown that UCHL5 promotes tumorigenesis, its role in lung cancer remains largely unknown." (PMID 33046988, 2020). "It has also been reported that the DUB inhibitor NiPT, which also blocks both Uchl5 and Usp14, induces autophagy in A549 and NCI-H1299 lung cancer cell lines." (PMID 39912491, 2025).
rectal cancer (2 papers, 2018 to 2020). A primary or metastatic malignant neoplasm that affects the rectum. "Recently, we reported that the proteasome-associated deubiquitinating enzyme UCHL5/Uch37 is a new prognostic marker in both rectal cancer and pancreatic ductal adenocarcinoma." (PMID 29474458, 2018). "Additionally, patients with high cytoplasmic UCHL5 immunoreactivity had increased survival in lymph node-positive (Dukes C/stage III) rectal cancer." (PMID 29474458, 2018). "We recently demonstrated that patients with high UCHL5 nuclear positivity in PDAC, and strong positive UCHL5 expression in lymph-node-positive (Dukes C/stage III) rectal cancer, showed a more favorable prognosis." (PMID 29474458, 2018).
thyroid cancer (2 papers, 2025 to 2026). "Similarly, UCHL5 demonstrated a significant increase in positive staining, from 0% (0/11) in normal tissues to 75% (6/8) in PTC and 100% (5/5) in ATC samples, highlighting the notable upregulation of USP14 and UCHL5 in thyroid cancer compared to normal thyroid tissues." (PMID 40804247, 2025).
atherosclerosis (1 paper, 2023). A disease characterized by the build-up of fatty material and calcium deposition in the arterial wall resulting in partial or complete occlusion of the arterial lumen. "UCHL5 modified by METTL14/YTHDF1 axis could facilitate the inflammation and vascular remodeling in atherosclerosis by activating the NLRP3 inflammasome." (PMID 37441706, 2023).
Fanconi anemia (1 paper, 2023). Fanconi anemia (FA) is a hereditary DNA repair disorder characterized by progressive pancytopenia with bone marrow failure, variable congenital malformations and predisposition to develop hematological or solid tumors. "The DUB proteins USP1, OTUB1, UCHL5, USP7, and PSMD14 were reported to contribute to double-strand break repair, USP1 to Fanconi anemia pathway, USP1 and USP7 to translesion repair, USP7 and USP47 to base excision repair, and USP7 and USP45 to nucleotide excision repair." (PMID 37892185, 2023).
intestinal cancer (1 paper, 2018). "Positive UCHL5 immunoexpression associated with intestinal cancer type (p = 0.004), but not with any of the other clinicopathological variables." (PMID 29474458, 2018).
kidney damage (1 paper, 2024). "Although kidney damage which may cause complex urogenital symptoms, including proteinuria, may potentially contribute to the elevation of UCHL5 in the blood, this cannot be the sole cause of the dramatic change of UCHL5 in the blood." (PMID 39034372, 2024).
liver disease (1 paper, 2021). "Understanding the inflammasome activation and role of UCHL5 pathogenesis of liver disease in the HCV-infected liver can help in generating different therapeutic strategies to target underlying liver disease as well as novel strategies to inhibit HCV infection." (PMID 34431717, 2021).
lymphoma (1 paper, 2018). A malignant (clonal) proliferation of B- lymphocytes or T- lymphocytes which involves the lymph nodes, bone marrow and/or extranodal sites. "WP1130 (WP) is a small molecule inhibitor of multiple DUBs (USP9X, 5, 14, UCHL5) that increases cl-PARP and poly-Ub accumulation in lymphoma cells and decreases the oncogenic transcription factor ERG, a key driver of PCa27,48." (PMID 30177856, 2018).
melanoma (1 paper, 2023). A malignant, usually aggressive tumor composed of atypical, neoplastic melanocytes. "In addition, the DUB inhibitor VLX1570, which inhibits USP14 and UCHL5, has undergone phase 1 clinical trials in multiple melanoma patients." (PMID 37107644, 2023).
non-small cell lung carcinoma (1 paper, 2022). A group of at least three distinct histological types of lung cancer, including non-small cell squamous cell carcinoma, adenocarcinoma, and large cell carcinoma. "Palladium pyrithione complex (PdPT), a broad-spectrum DUB (including USP7, USP10, USP14, USP15, USP25, and ubiquitin C-terminal hydrolase L5 (UCHL5) inhibitor, can also cause GPX4 protein ubiquitinated degradation in non-small cell lung cancer cells." (PMID 36551253, 2022).
pancreatic adenocarcinoma (1 paper, 2024). "Furthermore, a study revealed that UCHL5 promotes cancer stemness and tumor progression in pancreatic adenocarcinoma (PAAD) by stabilizing ELK3, demonstrating its diversity in tumor regulation." (PMID 39068672, 2024).